MIR17HG (miR-17-92a-1 cluster host gene)
Diseases named in the same sentence as MIR17HG in open-access papers (continued):
Sharing a sentence is not in itself a finding about the gene and the disease.
Feingold syndrome (1 paper, 2018). Feingold syndrome (FS), also known as oculo-digito-esophageal-duodenal (ODED) syndrome, is a rare inherited malformation syndrome characterized by microcephaly, short stature and numerous digital anomalies and is comprised of two subtypes: FS type 1 (FS1) and FS type 2 (FS2). "Heterozygous mutations in MYCN or MIR17HG in humans cause Feingold syndrome that is characterized by skeletal developmental defects including microcephaly, short stature, and brachysyndactyly with diminished middle phalanxes." (PMID 29636449, 2018). "Feingold syndrome is a skeletal dysplasia caused by mutations in MYCN or MIR17HG, but it is not clear if these mutations lead to pathology via a common molecular mechanism." (PMID 29636449, 2018).
germ cell tumor (1 paper, 2021). A benign or malignant, gonadal or extragonadal neoplasm that originates from germ cells. "Indeed, SMARCB1 associated with the promoter region of MIR17HG in ATRT cell lines, pluripotent human germ cell tumor-derived cells and human liver cancer cells." (PMID 34439268, 2021).
inflammatory bone diseases (1 paper, 2024). "Additionally, exploring the therapeutic potential of targeting MIR17HG in clinical settings could pave the way for novel treatments for inflammatory bone diseases." (PMID 39145884, 2024).
ocular toxoplasmosis (1 paper, 2019). Ocular toxoplasmosis is an infection in the eye caused by the parasite, Toxoplasm a gondii. "In our results—obtained in human retinal Müller cells, which have direct relevance to ocular toxoplasmosis—LINC01105, BANCR, MIR17HG, MIR155HG, lnc-SGK1, MEG3, KCNQ1OT1, NEAT1, NeST, and MALAT1 were the most dysregulated lncRNAs with known immunologic activities." (PMID 31547203, 2019).
osteoarthritis (1 paper, 2024). A noninflammatory degenerative joint disease occurring chiefly in older persons, characterized by degeneration of the articular cartilage, hypertrophy of bone at the margins and changes in the synovial membrane. "Recent research has linked MIR17HG to osteoarthritis, suggesting its involvement in other bone diseases such as osteomyelitis and osteoarthritis, where inflammation is a key factor." (PMID 39145884, 2024).
psoriasis (1 paper, 2025). An autoimmune condition characterized by red, well-delineated plaques with silvery scales that are usually on the extensor surfaces and scalp. "MIR17HG is a precursor RNA for the mir17-92 cluster, which haspreviously been reported to promote the proliferation and the chemokine production of keratinocytes, being implicated in psoriasis pathogenesis." (PMID 40725409, 2025).
renal carcinoma (1 paper, 2017). A carcinoma arising from the epithelium of the renal parenchyma or the renal pelvis. "Out of the unique set of genes detected by BNNPT, a few were reported to be relevant to renal cancer or disease: CDCP1, GSTT1, E2F3, MAPK1, SALL4, SIRT1, ADAMTS13, Gfrα1, ASPH, MIR17HG, APOE, BMP4, RCOR1, NUMB and SEC63." (PMID 28986523, 2017).
Sepsis (1 paper, 2024). Sepsis is defined as life-threatening organ dysfunction caused by a dysregulated host response to infection. "In conclusion, this work discovered considerable MIR17HG overexpression in macrophages treated with circulating exosomes from sepsis-affected animals." (PMID 38540147, 2024). "In conclusion, this study found significant MIR17HG overexpression in macrophages treated with circulating exosomes from mice with sepsis." (PMID 38540147, 2024).
squamous cell carcinoma (1 paper, 2020). A carcinoma arising from squamous epithelial cells. "It was observed that MIR17HG was downregulated in both adenocarcinoma (0.4 vs. 0.54) and squamous cell carcinoma (0.76 vs. 0.88), which are two major subtypes of NSCLC." (PMID 32228546, 2020).
Stroke (1 paper, 2026). Sudden impairment of blood flow to a part of the brain due to occlusion or rupture of an artery to the brain. "It is particularly noteworthy that LncRNA KCNQ1OT1, MALAT1, MIR17HG, and RMST are upregulated in hS3-treated healthy neuronal cultures, as these lncRNAs are known to be highly upregulated in stroke and inflammatory diseases." (PMID 41602576, 2026). "Similarly, MIR17HG, the host gene of the MIR17-92 cluster, promotes NPC survival after stroke and plays a critical role in Treg development in EAE." (PMID 41602576, 2026).
T-cell lymphoma (1 paper, 2018). "In T-cell lymphoma GATA3 and MIR17HG are overexpressed while in early T-cell progenitor ALL these genes are inactivated or downregulated." (PMID 29746601, 2018).
cancer (17 papers, 2014 to 2025). A tumor composed of atypical neoplastic, often pleomorphic cells that invade other tissues. "Recent experimental evidence indicates that mutation or deregulation of the MIR17HG gene (miR-17 ~ 92 cluster) contributes to the pathogenesis of a variety of human diseases, including cancer and congenital developmental defects." (PMID 24739087, 2014). "However, emerging evidence suggests that loss of function of MIR17HG might contribute to the development and progression of other types of cancers, implicating a tumor suppressor function." (PMID 25069832, 2014). "We also investigated commonly shared lncRNAs between COAD and READ (CRCs) and found the presence of MAGI2-AS3, GAS5, SNHG1, KCNQ1OT1, SNHG20, and MIR17HG in both cancers." (PMID 35140741, 2021). "Compared to other family members of MIR17HG, miR-18a is less studied, and only limited information is available regarding its function in human cancer cells." (PMID 25069832, 2014). "Notably, MEG3, MIAT, Malat1, SNHG20, SNHG12, Ftx, Pvt1, Mir9-3hg expression in cancer immune cells was associated with an immunosuppressive phenotype, while H19, SNHG6, Trp53cor1, MiR17hg and MiR142hg were linked to a pro-inflammatory phenotype in cancer." (PMID 40527978, 2025). "MIR17HG is a member of lncRNAs located in a region of human chromosome 13q31, which was shown to play an important role in the development and progression of several human cancers through regulating tumor growth and apoptosis." (PMID 33299861, 2020). "Numerous recent studies have confirmed that MIR17HG exhibits complex links to cancer metastasis." (PMID 31186404, 2019). "Moreover, our results also demonstrate that the type II interferon IFN-γ, which is mediated by IRF-1, can attenuate MIR17HG expression in GC cells and therefore further links the tumour immune response to cancer cell metastasis." (PMID 31186404, 2019). "Various lncRNAs such as LINC00857, MIR17HG, NKX2-1-AS1, LINC01234, and FAM225A have been found to manipulate specific miRNAs to influence cancer cell behavior." (PMID 39172101, 2024). "Our present study first showed that MIR17HG enhanced glycolysis in CRC cells, which supplemented the roles of MIR17HG in cancers." (PMID 34145399, 2021). "They reported that the MicroRNA-17-92 Family, also named as “miR-17/92 cluster”, is located in the locus of the non-protein-coding gene MIR17HG, which is dysregulated in cancer tissue, thereby affecting cell cycle, apoptosis and other crucial processes." (PMID 37007972, 2023). "In conclusion, MIR17HG was downregulated in NSCLC and may upregulate miR-142-3p through methylation pathway to promote its expression, thereby downregulating Bach-1 and suppress cancer cell invasion and migration." (PMID 32228546, 2020).
tumor (17 papers, 2014 to 2025). "Furthermore, our data showed that MIR17HG expression was significantly higher in tumor tissues associated with liver metastasis than in liver metastasis-free tissues." (PMID 34145399, 2021). "Significantly reduced expression levels of MIR17HG were observed in NSCLC tissues compared to that in non-tumor tissues in the 60 NSCLC patients included in this study." (PMID 32228546, 2020). "We also observed the slightly lower levels of MIR17HG in NSCLC tissues compared to that in non-tumor tissues by analyzing TCGA dataset." (PMID 32228546, 2020). "Remarkably, inhibition of FXR1 and MIR17HG in combination largely reduced xenograft tumor growth and prolonged the nude mice survival." (PMID 30691465, 2019). "More importantly, knockdown of FXR1 and MIR17HG in combination significantly reduced xenografts tumor growth." (PMID 30691465, 2019). "Thus, GATA3 and MIR17HG operate in particular T-cell malignancies as oncogenes or tumor suppressors." (PMID 29746601, 2018). "Therefore, to gain a more complete understanding of the physiological impact of MIR17HG deregulation in cancer, a detailed investigation of each individual MIR17HG family member in multiple types of tumor cells is required." (PMID 25069832, 2014). "For instance, silencing lncRNAs such as MEG3, FTX, and MIAT in tumor-infiltrating myeloid or T cells, or enhancing expression of pro-inflammatory lncRNAs like NEAT1 or MIR17HG in T cells, may reduce immunosuppression, promote infiltration, and enhance activation of anti-tumor immunity." (PMID 40527978, 2025). "SNHG6 was expressed at the tumor edge and in the pseudopalisading regions around necrosis, but most lncRNAs (Pvt1, SNHG12, H19, Neat1, Malat1, Mir17hg and Ftx) were expressed around the necrotic tumor regions." (PMID 40527978, 2025). "Among the lncRNAs, eight were overexpressed in tumor tissues (SNHG3, AC099850.4, MIR17HG, AL033527.3, AC091057.1, AC026333.4, AL512506.1, and SCAT2)." (PMID 35778697, 2022). "Therefore, MIR17HG may play tumor suppressive roles in NSCLC." (PMID 32228546, 2020). "This downregulation was further confirmed by measuring the expression levels of MIR17HG in NSCLC and non-tumor tissues from NSCLC patients." (PMID 32228546, 2020). "Furthermore, mir-17 and 20a positively correlate with MYC and MIR17HG, and, conversely, negatively correlated with FOXA1 in overall primary tumor samples." (PMID 36550153, 2022). "Given the anti-MIR17HG-mediated metastatic effects of IRF-1 in vitro, we subsequently questioned whether the inhibition of IRF-1 affects tumour metastasis in vivo." (PMID 31186404, 2019). "Interestingly, the MIR17HG/miR-138-5p/hexokinase (HK1/2) pathway enhances glycolysis, and increased lactate (a metabolite of glycolysis) that activates the p38/ELK1 pathway; this promotes the expression of MIR17HG and, forms a positive feedback loop for promoting tumor invasion and metastasis." (PMID 38201487, 2023).
infection (2 papers, 2019 to 2020). The state of being infected such as from the introduction of a foreign agent such as serum, vaccine, antigenic substance or organism. "Thus, expression of LINC00968, LINC01105, lnc-SGK1, MHRT, MIR17HG, and NeST were only or largely impacted in GPHT infection." (PMID 31547203, 2019).
MIR17HG also shares sentences with these, for which no sentence is quoted: acute myeloid leukemia (2 papers); adenocarcinoma (2); Autoimmunity (2); nasopharyngeal carcinoma (2); osteosarcoma (2); ovarian cancer (2); autoimmune disease (1); breast tumors (1); colorectal adenocarcinoma (1); diffuse large B-cell lymphoma (1); endometrial cancer (1); Feingold syndrome type 2 (1); hepatocellular carcinoma (1); liver cancer (1); lung diseases (1); medulloblastoma (1); metastasis (1); multiple sclerosis (1); pancreas adenocarcinoma (1); pancreatic cancer (1); rectal cancer (1); rhabdomyosarcoma (1); rheumatoid arthritis (1); stomach cancer (1).